SESN1 (sestrin 1)
Description:
Functions as an intracellular leucine sensor that negatively regulates the TORC1 signaling pathway through the GATOR complex. In absence of leucine, binds the GATOR subcomplex GATOR2 and prevents TORC1 signaling. Binding of leucine to SESN2 disrupts its interaction with GATOR2 thereby activating the TORC1 signaling pathway. This stress-inducible metabolic regulator may also play a role in protection against oxidative and genotoxic stresses (By similarity). May positively regulate the transcription by NFE2L2 of genes involved in the response to oxidative stress by facilitating the SQSTM1-mediated autophagic degradation of KEAP1. Moreover, may prevent the accumulation of reactive oxygen species (ROS) through the alkylhydroperoxide reductase activity born by the N-terminal domain of the protein (By similarity). Was originally reported to contribute to oxidative stress resistance by reducing PRDX1. However, this could not be confirmed (By similarity).
Synonyms: PA26; SEST1
Tractability: PROTAC: ubiquitination databases record sites on it.
Gene: Protein-coding gene on chromosome 6 (108,984,309 to 109,095,074, reverse strand). Ensembl gene ENSG00000080546.
Subcellular location: Nucleus; Cytoplasm
Subcellular location (Human Protein Atlas): Nucleoli fibrillar center; Nucleoplasm
Pathways (Reactome):
Cellular responses to stimuli: Amino acids regulate mTORC1; KEAP1-NFE2L2 pathway
Gene Ontology:
Molecular function: L-leucine binding; protein binding; oxidoreductase activity, acting on peroxide as acceptor
Biological process: cellular oxidant detoxification; cellular response to amino acid starvation; cellular response to glucose starvation; negative regulation of TORC1 signaling; reactive oxygen species metabolic process; cellular response to L-leucine; cellular response to leucine starvation; positive regulation of macroautophagy; cellular response to amino acid stimulus; negative regulation of cell growth; regulation of response to reactive oxygen species
Cellular component: cytoplasm; fibrillar center; GATOR2 complex; nucleoplasm; nucleus; cytosol
Genetic constraint (gnomAD): Loss-of-function variants: 24 observed, 47.73 expected, observed/expected ratio (o/e) 0.5, 90% interval 0.36 to 0.71. The upper end of that interval is the gene's LOEUF score, 0.71, which puts it in group 2 of 6, group 1 being the genes least tolerant of losing a copy. Missense variants: 466 observed, 566.77 expected, observed/expected ratio (o/e) 0.82, 90% interval 0.76 to 0.89. Synonymous variants: 164 observed, 188.37 expected, observed/expected ratio (o/e) 0.87, 90% interval 0.77 to 0.99.
Homologues: Orthologues: chimpanzee SESN1 (100% identical), guinea pig SESN1 (95% identical), macaque SESN1 (95% identical), rabbit SESN1 (94% identical), rat Sesn1 (94% identical), dog SESN1 (85% identical), mouse Sesn1 (82% identical), pig SESN1 (79% identical), tropical clawed frog sesn1 (76% identical), zebrafish sesn1 (68% identical), Drosophila melanogaster Sesn (39% identical), Caenorhabditis elegans sesn-1 (23% identical). Paralogues in human: SESN3 (54% identical), SESN2 (50% identical).
Diseases named in the same sentence as SESN1 in open-access papers:
SESN1 is named in the same sentence as 50 diseases in open-access papers, as found by Europe PMC text mining. Sharing a sentence is not in itself a finding about the gene and the disease. The quoted sentences say what the papers report.
lung carcinoma (7 papers, 2015 to 2025). "Knockout of SESN1&2 increased the proliferation of A549 lung cancer cells, with the rate of proliferation increasing progressively with each Sestrin knocked out." (PMID 40361504, 2025). "However, the precise role of SESN1/2 in the regulation of lung carcinogenesis needs to be verified in more detailed studies based on lung cancer animal models." (PMID 31857853, 2019). "Therefore, we conducted studies based on a mouse lung cancer model and human lung adenocarcinoma A549 cells to evaluate the potential impact of SESN1 and SESN2 on lung carcinogenesis." (PMID 31857853, 2019). "Our current data indicate that the expression levels of the SESN1 and/or SESN2 genes are often diminished in human lung cancers and suppression of SESN1/2 may support tumor growth and/or progression through such mechanisms as stimulation of cell growth, proliferation, mutagenesis, and angiogenesis." (PMID 31857853, 2019). "SESN1 and SESN2 frequently exhibit reduced expression in lung tumours, with decreased SESN2 levels marking a poor prognosis for lung cancer patients." (PMID 40361504, 2025). "A recent study in A549 cells suggests that SESN1 and SESN2 regulate aberrant STAT3 activation in lung cancer, limiting malignant proliferation and enhancing sensitivity to apoptosis." (PMID 40361504, 2025). "In previous studies, the down-regulation of SESN2 was shown to accelerate both colitis and colon carcinogenesis, while SESN1 and SESN3 were found to be strongly down-regulated in various types of cancer tissues, such as lung cancers and lymphomas." (PMID 35195231, 2022). "A study on lung cancer in a mouse model showed that knockout of either Sesn1, Sesn2, or both does not impact tumour formation." (PMID 40361504, 2025). "EZH2 is overexpressed in many human lung cancers, correlating with poor prognosis, and EZH2 may be responsible for the downregulation of SESN1 expression in lung cancers." (PMID 31857853, 2019). "To study the potential impact of the SESN1 and SESN2 genes in lung carcinogenesis, we analyzed mRNA expression of these genes using The Cancer Profiling Expression Array (Clontech) containing equal amounts of mRNA from matched human lung cancers and normal tissues from the same patient." (PMID 31857853, 2019).
cardiac hypertrophy (5 papers, 2017 to 2025). "To further confirm the possible effect of Sestrin 1 in cardiac hypertrophy, we investigated the ‘gain and loss’ phenotype of Sestrin 1 in PE‐triggered cardiomyocytes hypertrophy." (PMID 28181410, 2017). "In the present study, we take the lead to study the role of Sestrin 1 in cardiac hypertrophy and the underlying mechanisms." (PMID 28181410, 2017). "Thus, considering the potential role of Sestrin 1 in the modulation of autophagy, we examined the regulatory effect of Sestrin 1 in PE‐induced cardiac hypertrophy and explored the underlying mechanisms in this study." (PMID 28181410, 2017). "In experimental models of pressure-overload and phenylephrine-induced cardiac hypertrophy, Sestrin 1 gene and protein expression declined which correlated with decreased macroautophagy." (PMID 29576856, 2018). "To further evaluate the ability of Sestrin 1 to inhibit cardiac hypertrophy, we examined the effect of Sestrin 1 overexpression on cardiac hypertrophy." (PMID 28181410, 2017). "Knockdown of Sestrin 1 by RNAi deteriorated PE‐induced cardiac hypertrophy, whereas the overexpression of Sestrin 1 by adenovirus transfection blunted hypertrophy." (PMID 28181410, 2017). "In the present study, we discovered significant decline of Sestrin 1 in AB‐induced pressure overload cardiac hypertrophy and PE‐induced cardiac hypertrophy." (PMID 28181410, 2017). "Next, we examined the effect of Sestrin 1 knockdown on cardiac hypertrophy by analysing hypertrophic indicators, including ANP, BNP and cardiomyocyte surface area after 24 hrs of incubation with PE." (PMID 28181410, 2017). "Combining with our previous study demonstrating that activated AMPK inhibits cardiac hypertrophy via promoting autophagy, our current study further indicated that Sestrin 1 modulates AMPK/mTORC1/autophagy axis to fulfil its antihypertrophic function." (PMID 28181410, 2017). "To determine the alteration of Sestrin 1 expression in PE‐induced cardiac hypertrophy, we examined the changes in Sestrin 1 expression 24 hrs after PE treatment." (PMID 28181410, 2017). "We discovered that as the progression of cardiac hypertrophy and deterioration of cardiac function, Sestrin 1 mRNA and protein expression significantly declined." (PMID 28181410, 2017). "Taken together, our data strongly indicated that Sestrin 1 regulated both pressure overload cardiac hypertrophy and PE‐induced cardiac hypertrophy." (PMID 28181410, 2017). "Taken together, our data indicate that Sestrin 1 regulates AMPK/mTORC1/autophagy axis to attenuate cardiac hypertrophy." (PMID 28181410, 2017). "Consistent with the previous results, our results showed that Sestrin 1 knockdown significantly impaired autophagy, suggesting that Sestrin 1 expression is essential for maintaining autophagy in the process of cardiac hypertrophy." (PMID 28181410, 2017). "Our study showed that Sestrin 1 mRNA and protein expression declined in pressure overload cardiac hypertrophy and phenylephrine (PE)‐induced cardiac hypertrophy." (PMID 28181410, 2017). "In summary, our study revealed that Sestrin 1 ameliorates both PE‐ and AB‐induced cardiac hypertrophy; its positive regulation on autophagy by targeting AMPK/mTORC1 axis is one of the critical mechanisms involved." (PMID 28181410, 2017). "To further clarify the molecular mechanisms involved in the regulation of autophagy in cardiac hypertrophy by Sestrin 1, we examined the effect of Sestrin 1 on AMPK/mTOR pathway." (PMID 28181410, 2017). "Sestrin 1 may also play a regulatory role in several types of diseases, including cardiac hypertrophy and retinal diseases." (PMID 33883304, 2021). "Importantly, we found mRNA and protein levels of Sestrin 1 significantly decreased in cardiac hypertrophy." (PMID 28181410, 2017). "Importantly, Sestrin 1 targets at the AMPK/mTORC1/autophagy pathway to inhibit cardiac hypertrophy by interaction with AMPK which is responsible for autophagy regulation." (PMID 28181410, 2017).
cardiac hypertrophy (continued). "Moreover, we found that Sestrin 1 antagonized cardiac hypertrophy by positive regulation of autophagy." (PMID 28181410, 2017). "Furthermore, the evidence that overexpression of Sestrin 1 activated autophagy in the presence of PE directly proved that Sestrin 1 is a positive activator of autophagy in cardiac hypertrophy." (PMID 28181410, 2017). "To determine whether Sestrin 1 is involved in the regulation of pressure overload cardiac hypertrophy, we detected the alteration of Sestrin 1 expression in aortic banding (AB)‐induced cardiac hypertrophy." (PMID 28181410, 2017). "Previous studies that demonstrated the role of Sestrin 1 in the cardiovascular field are limited; how Sestrin 1 functions in cardiac hypertrophy remains unknown." (PMID 28181410, 2017). "Conversely, the adenoviral overexpression of Sestrin 1 significantly inhibited cardiac hypertrophy." (PMID 28181410, 2017). "Knockdown of Sesn1 significantly alleviated phenylephrine- (PE-) induced cardiac hypertrophy by regulating the AMPK/mTORC1/autophagy axis, while Sesn1 overexpression led to the opposite effect." (PMID 32626541, 2020). "However, the role of Sestrin 1 in cardiac hypertrophy remains unknown." (PMID 28181410, 2017).
breast carcinoma (4 papers, 2016 to 2020). "We found that both CAB39L and SESN1 mRNAs fulfilled those two criteria and this happened similarly in gastric cancer, head and neck and breast cancer cohorts of patients." (PMID 28698800, 2017). "On a similar note, Kaplan–Meier analysis showed that breast cancer patients with higher expression of both SESN1 and CAB39L exhibited better survival." (PMID 28698800, 2017). "Altogether these findings indicate that downregulation of miR-21-5p expression by metformin, followed by release of CAB39L and SESN1, contributed to attenuating the mTOR aberrant activity and rendering breast cancer cells more prone to cell death induced by a clinically relevant mTOR inhibitor." (PMID 28698800, 2017). "The overexpression of either CAB39L or SESN1 mimicked the effect of metformin, while the depletion of CAB39L or SESN1 increased both clonogenicity and migration of all the breast cancer cell lines tested." (PMID 28698800, 2017).
lymphoma (4 papers, 2014 to 2025). A malignant (clonal) proliferation of B- lymphocytes or T- lymphocytes which involves the lymph nodes, bone marrow and/or extranodal sites. "The EZH2X641Y mutation in lymphoma cells leads to mTORC1 activation via suppression of SESN1 transcription." (PMID 40361504, 2025). "The 6q21 locus, which includes SESN1, frequently undergoes deletion in human follicular lymphomas, and SESN1 expression is notably reduced in lymphomas that express the mutant EZH2X641Y protein." (PMID 40361504, 2025). "Furthermore, the knockout of SESN1 in the SU-DHL-10 lymphoma cell line abolished the apoptosis induced by GSK126, an inhibitor of EZH2’s methyltransferase activity." (PMID 40361504, 2025). "As we showed recently, a mutant form of histone methyltransferase EZH2, responsible for transcriptional repression of multiple genes in cancer cells, inhibits expression of SESN1 in lymphomas and restoration of SESN1 expression in the tumors leads to suppression of lymphomagenesis in mice." (PMID 31857853, 2019). "Hence SESN1-mediated mTOR pathway inhibition may be an important mechanism of reintroducing GRag sensitivity in EZH2 mutant lymphoma cells after EPZ-6438 treatment." (PMID 25493630, 2014).
atherosclerosis (3 papers, 2022 to 2025). A disease characterized by the build-up of fatty material and calcium deposition in the arterial wall resulting in partial or complete occlusion of the arterial lumen. "SESN1 has been demonstrated to be an atherosclerosis-related marker, and SESN1 can alleviate the release of inflammatory factors in macrophages of an atherosclerosis animal model." (PMID 35043753, 2022). "Accordingly, FOXP1 and SESN1 might be used as promising targets for treatment of atherosclerosis." (PMID 35043753, 2022).
follicular lymphoma (3 papers, 2019 to 2025). Follicular lymphoma is a form of non-Hodgkin lymphoma characterized by a proliferation of B cells whose nodular structure of follicular architecture is preserved. "SESN1 is co-regulated with FOXO3 and is a target of the EZH2Y641X gain of function mutation and of focal deletions in follicular lymphoma." (PMID 36670235, 2023). "Moreover, genetic and pharmacological inhibition of the methyltransferase EZH2 controls SESN1 expression and its subsequent activity on mTORC1 in follicular lymphoma." (PMID 31546746, 2019).
head and neck cancer (3 papers, 2018 to 2024). A primary or metastatic malignant neoplasm affecting the head and neck. "Overall, an up-regulation of PHPT1, CCNG1, CDKN1A, GADD45, and SESN1 was found in endometrial and head and neck cancer patients at all time points with the exception of SESN1." (PMID 29474504, 2018). "SESN1 as a novel molecular target can improve head and neck cancer treatment." (PMID 35865544, 2022).
lung adenocarcinoma (3 papers, 2019 to 2025). A carcinoma that arises from the lung and is characterized by the presence of malignant glandular epithelial cells. "EZH2 silencing in lung adenocarcinoma cells attenuates cell cycle progression, cell growth and invasion that can be linked to the re-activation of SESN1." (PMID 31857853, 2019). "In human lung adenocarcinoma cells, the inactivation of SESN1 supports cell proliferation and suppresses glucose starvation." (PMID 37667226, 2023). "We have previously reported that silencing of SESN1 or SESN2 stimulates the growth of lung adenocarcinoma A549 tumor xenografts in nude mice, which is in contrast with the negative effect of SESTRINs’ inactivation on tumor growth in the KrasLSL-G12D-based mouse model." (PMID 31857853, 2019). "Our previous studies showed that inactivating SESN1&2 in lung adenocarcinoma A549 cells accelerates cell proliferation and confers resistance to cell death without affecting mTORC1 activity, suggesting that SESN1&2 modulate cellular processes via mTORC1-independent mechanisms." (PMID 39985075, 2025). "Our analysis of mTORC1 activity in SESN1&2 knockout (SESN1&2 KO) cells demonstrated that inactivation of SESN1&2 in lung adenocarcinoma A549 cells does not affect phosphorylation of mTORC1 targets, and the GATOR-mTORC1 pathway is not responsible for the regulation of cell death by SESN1&2." (PMID 39985075, 2025). "However, we could not detect any effects of SESN1&2 inactivation on the phosphorylation of β-Catenin in lung adenocarcinoma cells." (PMID 39985075, 2025). "However, phosphorylation of AKT and S6 was not changed in the lung adenocarcinoma A549 cells with the knockout of the SESN1 and/or SESN2 genes, indicating that pro-oncogenic signaling pathways activated during carcinogenesis may overcome the need for SESTRINs to support the high activity of AKT." (PMID 31857853, 2019).